IGFBP7 (insulin like growth factor binding protein 7)
Diseases named in the same sentence as IGFBP7 in open-access papers (continued):
Sharing a sentence is not in itself a finding about the gene and the disease.
heart failure (continued). "Plasma levels of the senescence marker insulin-like growth factor binding protein 7 (IGFBP7) were associated with worse health outcomes, such as hospitalization, in a cohort of patients suffering from heart failure." (PMID 37887011, 2023). "IGFBP7 can be sampled from the peripheral blood and serum levels of this protein increase in atherosclerosis and heart failure with preserved ejection fraction and correlate with cardiac function." (PMID 37036839, 2023). "IGFBP7 is a new promising marker in cardiovascular medicine, and its role should be further investigated, not only in respect to vascular changes but also heart failure and left ventricular dysfunction." (PMID 35204773, 2022). "In this study, we demonstrate that cardiac fibroblasts are critically involved in the development of heart failure by inducing not only cardiac fibrosis but also cardiomyocyte secretory phenotype through Htra3-TGF-β-IGFBP7 axis." (PMID 35672400, 2022). "Receiver-operating characteristic analysis demonstrated that NT-proBNP had better ability to diagnose heart failure, whereas IGFBP7 had a higher power to determine the severity of heart failure." (PMID 35672400, 2022). "IGFBP7, a novel prognostic biomarker for heart failure, has been suggested also as a marker for diastolic dysfunction in patients with heart failure with preserved EF, at risk of disease progression." (PMID 34217226, 2021). "In addition to being a sensitive and specific biomarker for heart failure, IGFBP-7 mediates cardiac senescence by stimulating IGF-1R-dependent suppression of FOXO3a." (PMID 41226289, 2025). "Bio-ADM: Bioactive adrenomedullin; CA125: Carbohydrate antigen 125; eGFR: Estimated glomerular filtration rate; HF: Heart failure; IGFBP7: Insulin-like growth factor binding protein 7; sST2: Soluble Suppression of Tumorigenicity-2; TIMP-2: Tissue inhibitor of metalloproteinases-2." (PMID 41157213, 2025). "IGFBP7 has been described to be secreted by failing cardiomyocytes in advanced heart failure." (PMID 39045455, 2024). "In contrast, IGFBP7 levels determined on admission had no additional diagnostic value for confirming exacerbation of heart failure symptoms (AUC = 0.50; 95% CI = 0.38–0.62; p = 0.93)." (PMID 38673493, 2024). "Elevated levels of IGFBP7 were also found in patients with heart failure." (PMID 35204773, 2022). "IGFBP7 has been recently identified as a novel biomarker for heart failure and cardiac hypertrophy." (PMID 35204773, 2022). "Moreover, IGFBP-7 was identified as a HF biomarker in proteomic scans performed in a murine model of cardiac failure." (PMID 34046187, 2021). "IGFBP7 is associated with cardiac structural and functional abnormalities, including hypertrophy, diastolic dysfunction and poor prognosis in patients with heart failure (HF) with and without atrial fibrillation (AF)." (PMID 34217226, 2021). "Interestingly, suppression of TIMP1 in mice has been linked to maintenance and expansion of stem cells with no increased risk of cancer, while the serum level of IGFBP7 is a marker of tissue aging and heart failure." (PMID 33512769, 2021). "Importantly, IGFBP-7 also plays a critical role in heart failure." (PMID 41226289, 2025). "Previous studies have suggested that the IGFBP7 protein may be a good biomarker in heart failure." (PMID 38673493, 2024). "Similarly, failing cardiomyocyte-specific secretory phenotype and its secreted cytokine IGFBP7 might be potential therapeutic targets for heart failure." (PMID 35672400, 2022). "There are some promising novel biomarkers, such as galectin-3, ST2, FGF-21, IGFBP-7, GDF-15, and TGF-β, that provide good specificity in diagnosing diastolic dysfunction or overt heart failure in diabetic patients." (PMID 39335666, 2024). "Promising novel biomarkers that showed good performance in detecting diastolic dysfunction or heart failure in diabetic patients include galectin-3, ST2, FGF-21, IGFBP-7, GDF-15, and TGF-β." (PMID 39335666, 2024).
heart failure (continued). "Integrative analyses of single-cardiomyocyte transcriptome and plasma proteome in human reveal that IGFBP7, which is a cytokine downstream of TGF-β and secreted from failing cardiomyocytes, is the most predictable marker of advanced heart failure." (PMID 35672400, 2022). "TGF-β1 induced the expression of key fibrotic proteins collagen type 1 and MMP2, but also less well-known heart failure related proteins, such as OPG, IGFBP7, PAI, uPA, and U-PAR." (PMID 35360018, 2022). "IGFBP7 together with tissue metalloproteinase 2 (TIMP2) has been extensively studied as a putative biomarker of kidney failure secondary to both diabetes and ischemia, and in heart failure." (PMID 39280605, 2024). "Both IGFBP7 and GDF15 independently predict mortality and hospitalization for heart failure." (PMID 34217226, 2021). "Nonetheless, IGFBP7’s function may be affected by its microenvironment, as elaborated above, and it may exhibit opposite biological functions in strongly dysregulated environments, such as those found in NAFLD and heart failure." (PMID 39045455, 2024).
breast carcinoma (31 papers, 2010 to 2025). "A prospective cohort study demonstrated that low levels of IGFBP-7 protein and messenger RNA expression were associated with less aggressive breast cancer characteristics." (PMID 40199609, 2025). "The blast cells from the MRD − patients depicted the highest expression of IGHM, a gene associated with good prognosis in breast cancer, and IGFBP7, a marker of leukemia cell and chemosensitivity in AML." (PMID 37845689, 2023). "In human breast cancer tissue, down-regulation of IGFBP-7 was associated with down-regulation of retinoblastoma protein, cyclin E overexpression, and impaired prognosis." (PMID 33767994, 2021). "The aim of the present nested case-control study was to examine associations between pre- and postoperative circulating IGF-I, IGFBP-3 and IGFBP-7 levels, and risk of breast cancer recurrence." (PMID 33767994, 2021). "It was reported that loss of heterozygosity (LOH) causes loss of expression of IGFBP7 in breast cancer." (PMID 31183073, 2019). "IGFBP7 is a secretory protein that is increasingly associated with tumor inhibitory effects in colon and breast cancers." (PMID 24690739, 2014). "While the IGF-pathway has been implicated as a mediator of breast cancer progression and is also involved in the regulation of apoptosis, our results suggest a novel important role for IGFBP7 and IGF-signalling." (PMID 20673354, 2010). "Our purpose was to establish whether circulating IGF-I, IGFBP-3, and IGFBP-7 levels are related to recurrence-risk in breast cancer." (PMID 33767994, 2021). "This study aimed to investigate whether IGFBP7 levels and messenger ribonucleic acid (mRNA) expression are associated with the patient and tumor characteristics and prognosis in breast cancer." (PMID 34606580, 2021). "This study aimed to investigate whether IGFBP7 levels were associated with the patient and tumor characteristics and prognosis in breast cancer." (PMID 34606580, 2021). "Interestingly, high IGFBP7 serum levels have been linked to several factors that influence breast cancer risk, such as insulin resistance, obesity and increased risk of metabolic syndrome, which may increase the risk of type 2 diabetes mellitus." (PMID 34606580, 2021). "IGFBP7 functions as a tumour suppressor gene in breast cancer, thyroid cancer and melanoma by inducing cell apoptosis and cell senescence." (PMID 39351597, 2024). "In conclusion, low IGFBP7 gene expression identifies a subset of breast cancer patients for whom the addition of ganitumab/metformin to neoadjuvant chemotherapy results in a significantly improved pCR rate compared to neoadjuvant chemotherapy alone." (PMID 39362991, 2024). "Further studies are needed to elucidate the potential role of IGFBP7 in the context of breast cancer immunotherapy." (PMID 39362991, 2024). "Systematically administered IGFBP7 into mice with breast cancer cell line xenografts also resulted in reduced vessel density in xenografts sections." (PMID 39045455, 2024). "It has been IGFBP7 was reported to play tumor suppressive role in breast cancer, thyroid carcinogenesis and melanoma by induction of cell apoptosis and cell senescence." (PMID 36681667, 2023). "For example, IGFBP7 plays tumor-suppressive roles in melanoma, thyroid carcinogenesis, and breast cancer by induction of cell senescence and apoptosis." (PMID 36681667, 2023). "Previous studies indicated that IGFBP7 functions as a tumor suppressor in several tumors, including hepatocellular carcinoma, colorectal carcinoma, prostate cancer cells, and breast cancer." (PMID 35812369, 2022). "The prognostic impact of insulin-like growth factor binding protein 7 (IGFBP7) in breast cancer is unclear." (PMID 34606580, 2021). "The risk of breast cancer recurrence was evaluated in relation to preoperative low (T1), moderate (T2), or high (T3) tertile IGF-I, IGFBP-3, IGFBP-7 levels, or IGF-I/IGFBP-3 molar ratios between cases and matched controls." (PMID 33767994, 2021).
breast carcinoma (continued). "When IGFBP-7 is bound to the ligands for insulin and IGF-I receptors in breast cancer cells, IGFBP-7 neutralizes mitogenic signaling and induces senescence." (PMID 33767994, 2021). "Similar to insulin-like growth factor binding protein 3 (IGFBP3), IGFBP7 can either act as a tumor promoter or suppressor in many different cancer types, including breast cancer, but the reason for this dual-action remains to be elucidated." (PMID 34606580, 2021). "Downregulation and even deletion of IGFBP7 have been found in breast cancer, lung cancer, bladder cancer, colorectal cancer, prostate cancer and melanoma, and low levels of IGFBP7 in tumor tissues are correlated with poor prognosis." (PMID 31183073, 2019). "In breast cancer, IGFBP7 treatment inhibited cell growth and induced apoptosis and senescence, in vitro and in vivo, only in cell lines that were tested negative for HER2/neu, estrogen and progesterone." (PMID 25886299, 2015). "Such a downregulation of IGFBP7 by promoter methylation was previously observed in solid tumours including melanoma, prostate, lung and breast cancer as well as T-ALL, suggesting a common mechanism in cancer." (PMID 25887188, 2015). "The role of Igfbp7 in regulating cell proliferation has been extensively studied in breast cancer cells where forced expression of Igfbp7 decreases tumor cell growth in vivo and in vitro." (PMID 24505323, 2014). "Various experiments have shown that a tumor-suppressing gene reduces IGFBP7 expression in tumor tissues, such as those in breast cancer." (PMID 24349832, 2013). "Although we have presented prior evidence that high IGFBP7 expression by breast cancer tissue or high circulating levels of this protein are related to poor prognosis, this protein has not previously been studied in relation to the efficacy of IGF-1R targeted therapies." (PMID 39362991, 2024). "We report that low IGFBP7 gene expression identifies a subset of breast cancers for which the addition of ganitumab, an anti-IGF-1R monoclonal antibody, to neoadjuvant chemotherapy, substantially improved the pathological complete response rate compared to neoadjuvant chemotherapy alone." (PMID 39362991, 2024). "Our observation that that high IGFBP7 expression was associated with worse clinical outcome in SCAN-B, a large contemporary population-based breast cancer cohort unexposed to ganitumab, supports the concept that high IGFBP7 expression reveals more than increased resistance to ganitumab." (PMID 39362991, 2024). "We report, using data from the I-SPY trial, that breast cancer patients with tumors showing low IGFBP7 gene expression were more than twice as likely to achieve a pCR with neoadjuvant treatment using the combination of ganitumab/metformin, and chemotherapy compared to neoadjuvant chemotherapy alone." (PMID 39362991, 2024). "In breast cancer, the overexpression of IGFBP7 could contribute to the inhibition of cell proliferation and migration by inducing cell senescence and apoptosis pathways." (PMID 39351597, 2024). "The ECOTYPER data corroborate the notion that IGFBP7 expression may be used to classify distinct subtypes of the breast cancer microenvironment." (PMID 39362991, 2024). "IGFBP7 expression was upregulated in breast cancer, glioblastoma, and esophageal adenocarcinoma and downregulated in colorectal cancer, colon cancer, glioma, hepatocellular carcinoma, high-grade serous ovarian carcinoma, pancreatic cancer, and thyroid carcinoma." (PMID 37660019, 2023). "Increased IGFBP7 expression is related to a better survival in breast cancer and CHOL." (PMID 37088808, 2023). "The role of IGFBP-7 in modulating IGF-IR activity in breast cancer merits further study." (PMID 33767994, 2021). "However, the IGFBP-7 levels among patients with IGF-IRm positive tumors were inversely distributed among cases with breast cancer recurrence and recurrence-free controls." (PMID 33767994, 2021).
breast carcinoma (continued). "There is prior evidence that systemic IGF-I and IGFBP-3 are associated with risk of breast cancer, but IGFBP-7 has not been studied in this context." (PMID 33767994, 2021). "Alternatively, IGFBP7 levels might rise in response to more aggressive breast cancer to slow its spread." (PMID 34606580, 2021). "However, the role of IGFBP7 in breast cancer is unclear, and conflicting in vivo and in vitro data have been published." (PMID 34606580, 2021). "We investigated the prognostic impact of tumor-specific IGFBP7 levels in breast cancer." (PMID 34606580, 2021). "We hypothesized that we would observe an increased risk of breast cancer recurrence with elevated IGF-I and IGFBP-3 levels while elevated IGFBP-7 may confer better prognosis." (PMID 33767994, 2021). "IGFBP7 expression is correlated with breast cancer progression." (PMID 32500027, 2020). "To uncover the signal pathway mediating IGFBP7 upregulation, we analyzed the expression of Igfbp7/IGFBP7 in EC (bEND.3 cells and HUVECs) upon the stimulation of VEGFA and TGFβ, which can increase IGFBP7 expression in breast cancer and glioblastoma vasculature respectively." (PMID 33505428, 2020). "Because IGFBP7 has been shown to suppress the proliferation of breast cancer cells we hypothesized that Igfbp7 may also play a role in regulating the normal mammary gland development." (PMID 24505323, 2014). "Low expression of IGFBP7 may be a good independent prognostic indicator for breast cancer." (PMID 39351597, 2024). "In addition we choose to study IGFBP-7, which is less well evaluated in the breast cancer setting." (PMID 33767994, 2021). "Congruently, increased VEGF levels were recorded in lung tumors of IGFBP7−/− mice and administration of exogenous IGFBP7 reduced VEGF expression in breast cancer cell lines 1833 xenografts implanted in mice." (PMID 39045455, 2024). "This study assessed the impact of intraoperative fluid management on AKI in female breast cancer patients undergoing autologous breast reconstruction, utilizing novel urinary biomarkers (TIMP-2 and IGFBP-7)." (PMID 39048691, 2024). "Numerous studies have shown that changes in the expression of IGFBP7 (FSTL2) are also observed in various types of cancer, including HCC, breast cancer, gastrointestinal cancer, prostate cancer, and many others." (PMID 34440203, 2021). "The prognostic role of postoperative changes in IGF-I, IGFBP-3, IGFBP-7, or IGF-I/IGFBP-3 levels in relation to breast cancer recurrence was assessed." (PMID 33767994, 2021). "The role of systemic IGFBP-7 and its interplay with the IGF-IR in breast cancer merit further study." (PMID 33767994, 2021). "In the breast cancer cohort, the Diff (%) was − 124% for SDF-1β, 52% for IGF1, and 132% for IGFBP7, respectively, confirming that the approach can detect a 10-fold difference in protein levels, described by Diff (%) > 120%." (PMID 33267867, 2020). "Numerous studies have provided evidence that IGFBP3 and IGFBP7 are involved in a variety of cancers, including hepatocellular carcinoma (HCC), breast cancer, gastroesophageal cancer, colon cancer, prostate cancer, among many others." (PMID 32500027, 2020). "Some effects of alcohol in breast cancer are proposed to be mediated through the IGF system and might attenuate the anti-proliferative effect of IGFBP7 by decreasing serum IGF-I levels." (PMID 34606580, 2021). "Circulating IGFBP-7 levels overall were not an independent predictor of breast cancer recurrence in the present study cohort." (PMID 33767994, 2021). "Our findings support the notion that tumor-specific IGFBP7 acts as a promoter rather than a suppressor in breast cancer." (PMID 34606580, 2021). "No independent associations between IGFBP-7 or IGF-I/IGFBP-3 tertiles and breast cancer recurrence were observed (Ptrends>0.3)." (PMID 33767994, 2021).
breast carcinoma (continued). "Although IGFBP7 is present in almost all normal tissues, IGFBP7 is downregulated or even absent in a variety of tumor types, including breast cancer, lung cancer, bladder cancer, colorectal cancer, prostate cancer, melanoma and thyroid cancers." (PMID 31183073, 2019). "There was also a considerable increase in the expression of others genes described as stem cell markers and expressed in CD44high fractions of normal and breast cancer tissues, including FOXC1(∼11-fold), IGFBP7 (∼8.5-fold), PROCR (∼8.2-fold), LEF1 (∼6.7-fold) and ZEB1 (∼6.6-fold)." (PMID 24498388, 2014). "To date, the role of systemic IGFBP-7 in breast cancer progression has not been investigated." (PMID 33767994, 2021). "Furthermore, associations between pre- and postoperative levels of circulating IGF-I, IGFBP-3, and IGFBP-7 and breast cancer recurrence have not yet been studied." (PMID 33767994, 2021). "Low IGFBP7 rate had a significantly reduced survival, poor differentiation, and a higher tumor stage; in all examined breast cancer cases, 15% lacked IGFBP7 staining entirely, but 20% had weak staining, 32% intermediate and 33%, finally, showed strong staining." (PMID 32500027, 2020). "However, immunohistochemical studies have indicated that mammary carcinoma epithelium does not show, or only lightly shows, IGFBP7 staining." (PMID 32500027, 2020). "Similarly, TGF-β1 is a potent inducer of IGFBP7 and IGFBP7 is described as a stem cell marker expressed in CD44high but not in CD24high cell fractions of normal and breast cancer tissues." (PMID 24498388, 2014). "Meanwhile, postoperative changes in IGF-I, IGFBP-3, IGFBP-7, or IGF-I/IGFBP-3 molar ratios were not prognostic indicators of breast cancer recurrence once treatment was taken into account." (PMID 33767994, 2021). "The ability of IGFBP7 expression to identify breast cancers more likely to respond to ganitumab/metformin plus chemotherapy than to chemotherapy alone was most apparent in TNBC, where 66.7% of IGFBP7 Q1 tumors and no IGFBP7 Q4 tumors achieved pCR." (PMID 39362991, 2024).